NOD2 (nucleotide binding oligomerization domain containing 2)
Diseases named in the same sentence as NOD2 in open-access papers (continued):
Sharing a sentence is not in itself a finding about the gene and the disease.
type 1 diabetes (8 papers, 2009 to 2023). "It should be noted that in most studies using PRR-deficient NOD mice, the microbiome can be altered by the gene deficiency, which promotes a tolerizing influence and suppression of type 1 diabetes development, as in the case with NOD2-deficient NOD mice." (PMID 34177937, 2021). "Pattern recognition receptors (PRRs), such as Nod2, Nlrp3, Tlr2, Trl4, and Tlr9, are directly involved in type 1 diabetes (T1D) susceptibility." (PMID 32295112, 2020). "In type 1 diabetes, it has been suggested that microbial translocation to the pancreatic lymph nodes results in increased nucleotide-binding oligomerization domain containing protein 2 (NOD2) signaling, which results in enhanced Th1 and Th17 responses." (PMID 34296202, 2021). "Using a streptozotocin (STZ)-induced type 1 diabetes model, NOD2 deficiency, but not NOD1 or RIP2 deficiency, protected the mice from disease development." (PMID 34177937, 2021). "A further study has shown that the transfer of microbiota to pancreatic lymph nodes triggered the intracellular protein receptor nucleotide-binding oligomerization domain-containing 2 (NOD2) activation and contributed to the onset of type 1 diabetes." (PMID 35992113, 2022). "NOD2 expression or signaling was shown to be dependent on NOD2 polymorphism, vitamin D levels, hypoxia, HIV preexposure prophylaxis, and (nonsignificantly) type 1 diabetes status, potentially explaining how such noninfectious factors have been associated with TB." (PMID 37262021, 2023).
Cerebral ischemia (7 papers, 2018 to 2024). Restriction of arterial blood supply to the brain associated with insufficient oxygenation to support the metabolic requirements of the tissue. "Our previous study has reported that NOD2 aggravated cerebral lesion through initiating an inflammatory signaling pathway in mice following cerebral ischemia." (PMID 38012669, 2023). "Brazilein has been shown to reverse the elevated expression of TNF-α and nucleotide-binding oligomerization domain-containing protein 2 (NOD2) induced by cerebral ischemia and reperfusion in mice." (PMID 38174223, 2023). "Moreover, we previously demonstrated NOX2-derived ROS mediated NOD2-dependent inflammatory responses in cerebral ischemia-reperfusion." (PMID 30157869, 2018). "Following cerebral ischemia–reperfusion (I/R) injury, ARRB2 negatively regulates the NF-κB inflammatory signaling triggered by NOD2 (nucleotide-binding oligomerization domain-containing protein 2) through its interaction with TRAF6 in microglia." (PMID 39649720, 2024). "Naringenin also showed a neuroprotective profile in an animal model of brain ischemia, reducing apoptosis, inflammation, oxidative stress and neurological deficits through the modulation of claudin-5, MMP9, Nrf2, nucleotide oligomerization domain-like receptor 2 (NOD2) and NF-κB." (PMID 33383852, 2020).
colonic disease (7 papers, 2010 to 2023). "NOD2 risk allele carriers more often suffered from CD (p = 0.002) and carrying the NOD2 SNP was associated with colonic disease in these patients (p < 0.0001)." (PMID 29228965, 2017). "Patients carrying at least two NOD2 mutations and with pure colonic disease were extremely rare (n = 3)." (PMID 23300620, 2012). "In particular, carriers of at least one NOD2 mutations [P = 2.1e-7, OR 2.9 (1.9–4.3)], were at risk for the colonic disease, as well as the carriers of mutations in rs10761659 (ZNF365) [P = 6.6e-4, OR 2.1 (1.4–3.1)] and those in rs10000113 (IRGM) [P = 2.8e-4, OR 2.0 (1.4–3.0)]." (PMID 28052082, 2017). "A high occurrence of SNP rs9858542 (3p21) with ileal/colonic disease and inflammatory behaviour with SNP rs5743289 (NOD2) were identified." (PMID 21079743, 2010). "Three of these patients had mainly ileocolonic disease; the female CD patient (also not carrying one of the three NOD2 mutations) had isolated colonic disease." (PMID 25365249, 2014). "One of the early genes identified was NOD2/CARD15 on chromosome 16, which was analysed using polymerase chain reaction (PCR) sequence-specific primers to determine certain mutant alleles that were predictive of ileal Crohn’s disease but not colonic disease." (PMID 37762727, 2023).
diabetic nephropathy (7 papers, 2017 to 2025). "Additionally, NOD2, a key component of the NOD-like receptor family, significantly contributes to the pathological process of diabetic nephropathy; its deficiency can reduce renal damage in diabetic mice." (PMID 40698245, 2025). "NOD2 could participate in hyperglycemia-induced podocyte dysfunction and mediate inflammation and insulin resistance in diabetic nephropathy." (PMID 37153213, 2023). "Besides NOD2 and NLRP3, NOD-like receptor family CARD domain containing 5 (NLRC5), the largest NLR, also participates in the developments of many kidney diseases including ischemia–reperfusion injury and diabetic nephropathy in various manners." (PMID 31186034, 2019). "NOD2 could exert harmful impact on acute kidney injury induced by ischemia reperfusion or systemic administration of lipopolysaccharide/peptidoglycan, and could promote renal injury in diabetic nephropathy in canonical and noncanonical manners." (PMID 31186034, 2019).
ileitis (7 papers, 2012 to 2025). "Common experimental mouse models support the importance of the gut microbiota in the development of IBD, such as protein 2 (NOD2) deficient in the nucleotide-binding oligomerization domain, which typically has ileitis under standard feeding conditions." (PMID 40809439, 2025). "Furthermore, certain variants in NOD2 have been associated with more severe disease phenotypes including early-onset disease, ileitis, and strictures caused by fibrosis." (PMID 33042125, 2020). "CD risk variants of NOD2 were inversely associated with mucosal amino acids and EA but were positive with unknown compound X 7.61, with many metabolites moving in the opposite direction to CD and ileitis (η2 = 0.06–0.1, q < 0.1)." (PMID 35413017, 2022). "The role of NOD2 has been demonstrated in an ileitis-prone mouse model, where NOD2 ablation weakened the severity of spontaneous intestinal disease without affecting the microbial composition." (PMID 37876927, 2023). "Following peroral infection with 100 cysts of T. gondii strain ME49, NOD2-/- mice displayed more severe ileitis and higher small intestinal parasitic loads as compared to wildtype (WT) mice." (PMID 25141224, 2014). "Toxoplasma gondii induces a significant degree of dysbiosis with AIEC invasion being pronounced in mice deficient in the ileitis susceptibility gene NOD2, while it is notably reduced in mice lacking the pro-inflammatory CC chemokine receptor 2 (CCR2)." (PMID 40809439, 2025). "Furthermore, brains of NOD2-/- mice exhibited higher numbers of F4/80+ recruited macrophages and microglia cells as compared to WT mice 7 days upon ileitis induction (p<0.05)." (PMID 25141224, 2014). "Part of the cases of Crohn's ileitis is independent of NOD2 genotype and is linked to changes in the WNT pathway, mostly due to a decreased activity of transcription factor TCF4 that binds to enteric defensins gene promoters." (PMID 22236533, 2012). "Hence, upon ileitis induction NOD2-/- mice displayed more distinct local pro-inflammatory cytokine concentrations (i.e. in inflamed ilea) as compared to WT controls, whereas systemic (i.e. splenic) pro-inflammatory immune responses were less pronounced at day 7 p.i." (PMID 25141224, 2014).
influenza (7 papers, 2010 to 2024). An acute viral infection of the respiratory tract, occurring in isolated cases, in epidemics, or in pandemics; it is caused by serologically different strains of viruses (influenzaviruses) designated A, B, and C, has a 3-day incubation period, and usually lasts for 3 to 10 days. "In addition to the TLRs, RIG-I, NLRP3, and NOD2 have also been implicated in the immune response to influenza; however, the relative contribution of these PRRs to influenza-specific host defense requires additional study." (PMID 21108806, 2010). "Microbiota on different vaccine administration sites may also play a significant role e.g., nucleotide binding oligomerization domain-containing protein 2 (NOD2) sensing is associated with intranasal route and IgA induction is mostly associated with attenuated influenza vaccine." (PMID 39294611, 2024). "More recently, novel adjuvants and muramyl peptide derivatives targeting NOD2 have shown great potential at further increasing the immunogenicity of current vaccine constructs, including BCG, the nanoparticulate HIV-1 p24 vaccine, and the influenza subunit vaccine, among others." (PMID 35589853, 2022).
endometrial cancer (6 papers, 2010 to 2024). Primary or metastatic malignant neoplasm involving the endometrium (mucous membrane that lines the endometrial cavity). "For these reasons, we sought to determine if genetic variation in a number of TLRs and NOD genes (TLR2, TLR4, TLR9, NOD1 and NOD2) were associated with risk of developing endometrial cancer." (PMID 20646321, 2010). "Among these genes, CCR7, MYC and NOD2 have been reported in a large number of tumor studies, including endometrial cancer, while P2RX4, GNA15, and GPR132 genes have few molecular biological experiments to verify their role in endometrial cancer progress." (PMID 36207698, 2022). "Ten polymorphisms were genotyped in 191 endometrial cancer cases and 291 controls using real-time PCR: NOD1 (rs2075822, rs2907749, rs2907748), NOD2 (rs5743260, rs2066844, rs2066845), TLR2 (rs5743708), TLR4 (rs4986790) and TLR9 (rs5743836, rs187084)." (PMID 20646321, 2010). "Kaplan-Meier survival analysis and T-tests were used to evaluate the influence of the NOD1, NOD2, TLR2, TLR4 and TLR9 polymorphisms on the age of diagnosis of endometrial cancer." (PMID 20646321, 2010). "Moreover, TRIM22 inhibits endometrial cancer progression and improves prognosis by targeting the nucleotide binding oligomerization domain containing 2 (NOD2)/nuclear factor κB (NF-κB) signaling pathway." (PMID 38275298, 2024). "Eight IRGs were incorporated to construct a nomogram for survival prediction in endometrial carcinoma patients, including CCR7, GNA15, GPR132, LTA, MYC, NOD2, P2RX4 and P2RY2." (PMID 36207698, 2022).
graft versus host disease (6 papers, 2007 to 2017). An immune system disorder that occurs after allogeneic hematopoietic stem cell transplant and is a reaction of donor immune cells against host tissues. "Recent reports indicate that NOD2 gene mutations increase the risk for inflammatory bowl disease and the severity of graft-versus-host disease in bone marrow transplant patients." (PMID 24393249, 2014). "Recent reports have provided evidence that NOD2 gene variants influence the severity of graft-versus-host-disease (GVHD) and the transplant survival in bone marrow transplant (BMT) patients." (PMID 24393249, 2014). "In transplant literature NOD2 has been linked to increased risk of graft versus host disease and transplant-related mortality in hematopoietic stem cell transplantation." (PMID 23977330, 2013). "NOD2 was also found to be associated with increased risk of graft versus host disease and transplant related mortality in haematopoietic stem cell transplantation, and in kidney transplantation mutated NOD2 haplotypes are associated with higher rates of death with functioning graft." (PMID 23977330, 2013). "Additionally, recent data also indicate a pivotal role of the IBD-associated NOD2 SNPs in the pathogenesis of graft versus host disease (GvHD), one of the most deleterious complications after allogenic, haematopoietic stem cell transplantation (HSCT)." (PMID 21188218, 2010).
multiple sclerosis (6 papers, 2011 to 2024). A progressive autoimmune disorder affecting the central nervous system resulting in demyelination. "The same NOD2 polymorphism was found to be protective against multiple sclerosis and ameliorate the response to interferon-beta therapy, most likely as a part of a complex multidirectional system of genetic, immunological and environmental factors." (PMID 38755492, 2024). "NOD2 variants are associated with a high level of IL-17 in PBMC from patients with multiple sclerosis or with ocular toxoplasmosis stimulated with myelin-basic protein and soluble Toxoplasma antigen, respectively." (PMID 36795715, 2023). "Recently, it has been demonstrated that MIS416, a novel immunomodulatory microparticle that activates NOD-2 and TLR-9-signaling, has disease-modifying activity in multiple sclerosis models." (PMID 29321652, 2018). "Using a mouse model of multiple sclerosis, we are investigating the pathways by which activation of TLR9 and NOD2 may modify the innate immune environment and the subsequent T cell-mediated autoimmune responses." (PMID 24498172, 2014).
pneumococcal meningitis (6 papers, 2014 to 2023). An acute purulent infection of the meninges and subarachnoid space caused by Streptococcus pneumoniae, most prevalent in children and adults over the age of 60. "Variations within the NOD2 (rs2067085) and IRAK4 (rs4251552) were associated with pneumococcal meningitis disease outcome." (PMID 27432718, 2016). "Polymorphic variants of NOD2 rs2066847 were more common in patients with meningococcal meningitis but not with pneumococcal meningitis." (PMID 29754263, 2018). "Moreover, the activation of NF-κB in the brain tissues following infection with live S. pneumoniae was also significantly increased, which indicates that NOD2 mediated NF-κB activation in experimental pneumococcal meningitis." (PMID 25443778, 2014).
Salmonella Infections (6 papers, 2010 to 2025). Infections with bacteria of the genus SALMONELLA. "Collectively, these findings showed that ELMO1, NOD2, and their interaction are important in bacterial clearance and pathogenesis during AIEC-LF82 and Salmonella infection." (PMID 36694274, 2023). "As observed for AIEC-LF82, in case of Salmonella infection the absence of either ELMO1 or NOD2 or both resulted in a delayed bacterial clearance and significant decline in levels of IL-6 and IL-1β compared to C1 cells." (PMID 36694274, 2023). "The result of the present study reveals that NOD2 and ELMO1 can interact with each other directly and can influence the course of bacterial infection by regulating bacterial survival/clearance, ROS generation and immune response during AIEC-LF82 and Salmonella infection." (PMID 36694274, 2023).
type 2 diabetes (6 papers, 2007 to 2023). "Circulating monocytes from patients with type 2 diabetes have increased expression of both NOD1 and NOD2 as well RIPK2 and NF-κB." (PMID 37869013, 2023).
Chronic colitis (5 papers, 2017 to 2023). A chronic inflammatory disease of the large intestine (colon, cecum and rectum). "Further studies on the efficacy of this bacterial strain in preclinical models of chronic colitis is now awaited, especially in models exhibiting NOD2 deficiency." (PMID 36266398, 2022). "Following adaptive transfer of Nod2−/− T lymphocytes, immunodeficient mice developed less severe chronic colitis, for instance, pointing towards a rather disease-promoting feature of Nod2 signaling." (PMID 28592996, 2017). "Less severe chronic colitis could be observed following adoptive transfer of Nod2−/− T cells into immunocompromised mice, for instance, indicating that Nod2 signaling exacerbates large intestinal immunopathology." (PMID 28752081, 2017). "However, the reasons why the inactivation of NOD2 can result in chronic colitis remain largely speculative." (PMID 33431850, 2021). "The demonstration that SIgA reverse transcytosis in NOD2 KO mice favors the transport of a bound Ag, as reflected by the detection of specific immune responses, suggests that such a mechanism may be involved in the pathogenesis of chronic colitis." (PMID 33431850, 2021).
cystic fibrosis (5 papers, 2012 to 2025). Autosomal recessive disorder caused by pathogenic variants in the CFTR gene (cystic fibrosis transmembrane conductance regulator), which encodes a chloride and bicarbonate channel expressed in epithelial cells, and follow the diagnosis criteria. "In terms of that M. abscessus infection is dominant in patients with cystic fibrosis or immunosuppression, it seems to be important to know whether and how these underlying diseases modulate NOD2-mediated immune response in host." (PMID 29163541, 2017). "Likewise it was demonstrated that NOD1 but not NOD2, seems to play a role in chronic infection of airway by P. aeruginosa in cystic fibrosis patients." (PMID 25433669, 2014).
endotoxemia (5 papers, 2017 to 2022). "Among FMT recipients, the reduced expressions of Tlr4 and Nod2 compared to H reflected lower inflammation, implying that their improved metabolism might associate with the mitigated endotoxemia by receiving FMT from exercised donors." (PMID 30353027, 2018). "An important future goal is to understand divergence in Nod1 versus Nod2-induced metabolic effects and how these interact with endotoxemia." (PMID 28484277, 2017). "Thus, NLRP12 is dispensable for protecting mice against endotoxemia, but rather function as a negative regulator of NOD2 signaling in mice." (PMID 30559449, 2018).